LEP (leptin)
Diseases named in the same sentence as LEP in open-access papers (continued):
Sharing a sentence is not in itself a finding about the gene and the disease.
Obesity (continued). "In addition, leptin has a role in fertility, inflammation and tissue fibrosis and was identified as a risk factor for some cancers independent of obesity." (PMID 37189804, 2023). "However, due to leptin resistance, most forms of obesity of animals and human are associated with higher leptin levels rather than leptin deficiency." (PMID 37283763, 2023). "However, in people with obesity, leptin levels are often elevated, which may lead to resistance to its effects on appetite." (PMID 38201884, 2023). "Additionally, the presence of obesity induced by the HFD treatment may be associated with the parameter studied, namely leptin." (PMID 37175192, 2023). "Moreover, leptin prevents obesity by promoting satiety and reducing hunger and insulin sensitivity." (PMID 37363537, 2023). "However, chronic exposure to an elevated concentration of leptin in overweight/obesity might decrease the anti-tumor immune response of NK cell by inhibiting NK cell functions." (PMID 37258524, 2023). "Biallelic, (likely) pathogenic variants in LEP encoding leptin and LEPR encoding its receptor, leptin receptor (LEPR), that follow highly penetrant Mendelian inheritance lead to a congenital LEP-signaling-deficient state, causing very-early-onset severe obesity due to persistent hyperphagia." (PMID 37659411, 2023). "Leptin and adiponectin are two of the most abundant and well-studied adipokines in the brain, with particular emphasis on how the altered signaling of these adipokines in obesity may lead to cognitive dysfunction." (PMID 37600013, 2023). "Finally, a hypercapnic sensitivity study revealed that IN leptin rescued minute ventilation under hypercapnic conditions only in DIO male mice, which suggests that differential responses to IN leptin are attributable to different leptin sensitivities depending on sex and the obesity status." (PMID 38162827, 2023). "Moreover, previous studies reported a positive relationship between leptin levels and body fat, suggesting that leptin may play an important role in obesity." (PMID 38004115, 2023). "Obesity has been proposed as a activated metabolic gatekeeper of puberty, one of the key factors mediating this effect of obesity on puberty may be related to adipokines, especially leptin, which can directly stimulate gonadotropin secretion." (PMID 37255545, 2023). "This may have an important consequence since leptin is a primary adipokine linked to mechanisms leading to obesity and its complications regulating body mass via negative feedback between adipose tissue and hypothalamus." (PMID 36899850, 2023). "However, congenital and genetic defects of leptin result in obesity from internal mechanisms." (PMID 37937009, 2023). "Indeed, melatonin deficiency has been demonstrated to correlate with obesity, and the absence of melatonin leads to leptin resistance, making leptin treatments ineffective." (PMID 38001815, 2023). "However, during conditions of leptin resistance and hyperleptinemia as occurs in obesity of the MetS, this endocrine hormone and adipokine may function pathologically in regards to the development of HTN and CCVD." (PMID 36984562, 2023). "Notably, high testosterone levels in females may further disrupt mechanisms that prevent hyperphagia and adiposity, leading to exacerbated food intake, leptin resistance, and obesity." (PMID 37035685, 2023). "Finally, we will discuss the translational impact of these findings by evidencing the different mechanisms of action of drugs that are able to counteract the leptin-mediated effects and which may overcome the interplay between obesity and cancer." (PMID 37509120, 2023). "Indeed, participants with obesity have high levels of leptin in part through leptin resistance." (PMID 37362426, 2023). "However, the impact of these primary adipokines may be influenced by other factors, particularly in cases of elevated leptin levels in obesity, and these additional factors may counteract the favorable effects of leptin." (PMID 37021835, 2023).
Obesity (continued). "This is supported by a small cohort of 26 healthy human volunteers, in which significantly elevated levels of serum leptin were observed in individuals with obesity compared to those without, which was also associated with higher PD-1 expression on CD8+ T-cells." (PMID 37173907, 2023). "Considering that leptin levels in the bloodstream may strongly correlate with BMI and that leptin may mitigate sweet taste sensitivity, it may account for the reduction in sweet taste sensitivity often observed in people with obesity." (PMID 36904115, 2023). "This leptin-responsive neural circuit plays a fundamental role in the regulation of hyperphagia and metabolism in obesity, which suggests manipulation of the neural circuit pharmacologically could lead to novel obesity therapeutics." (PMID 37043384, 2023). "Obesity is a proinflammatory state, and the adipose tissue propagates inflammation by recruitment of macrophages via chemokines such as monocyte chemoattractant protein-1, and via elaboration of cytokines and chemokines such as leptin, interleukin-6, and tumor necrosis factor α." (PMID 37535415, 2023). "High circulating leptin might involve the dysregulation of pro-inflammatory cytokine in obesity." (PMID 37240656, 2023). "However, obesity disrupts this harmonious system, primarily through elevated leptin levels." (PMID 38264286, 2023). "A previous study discovered that plasma fasting insulin and leptin levels decreased in the GLP-1 (rhGLP-1) Beinaglutide (BN) treated mice, suggesting that BN could reduce hyperinsulinemia and hyperleptinemia associated with obesity." (PMID 37025414, 2023). "Likewise, the reasonable manipulation of leptin or the use of leptin-sensitizing agents could be a promising possibility of therapy for obesity and related metabolic dysfunctions in the future." (PMID 36674935, 2023). "When applied concurrently to mouse striatal slices, the effect of insulin plus leptin on evoked [DA]o is not additive, suggesting the elevated leptin levels that accompany obesity might also contribute to the loss of brain InsR sensitivity in this state." (PMID 36979453, 2023). "In addition to vascular changes, high fructose consumption has been shown to reduce plasma insulin and leptin levels and increase ghrelin concentrations, which may contribute to obesity and thus a pro-inflammatory state." (PMID 38201956, 2023). "Therefore, obesity could also reduce leptin responsiveness or shift the leptin setpoint by hindering leptin induction of its own receptor." (PMID 36769012, 2023). "Increased plasma levels of leptin have been reported following short-term hypoxia in middle-aged male individuals with obesity, indicating leptin production may be stimulated by hypoxia at high altitudes despite an observed reduction in the body weight of participants." (PMID 36441492, 2023). "Additionally, a positive correlation between Tenericutes and plasma leptin has been reported, which may relate to obesity pathophysiology." (PMID 38196849, 2023). "Therefore, the adiponectin to leptin (A:L) ratio is suggested as an index to estimate adipose tissue dysfunction, and may be useful to assess the net effects of these adipokines on obesity-related diseases, such as breast cancer." (PMID 37571390, 2023). "Consequently, the suppression of leptin and resistin expression may be an alternative means of combating obesity." (PMID 37371984, 2023). "The existence of receptors for leptin in chondrocytes and an increase in its level in serum and synovial fluid in OA suggest that leptin may be involved in the pathogenesis of OA, connecting obesity to OA." (PMID 36836794, 2023). "Moreover, the role of leptin/leptin receptors axis in obesity and the prognosis of CP is still unknown." (PMID 37509115, 2023). "Moreover, women show greater variability in leptin levels after stress, which indicates that leptin may have different effects on the development of obesity in response to stress depending on gender." (PMID 37959320, 2023).
Obesity (continued). "Obesity in their cohort may be responsible for the increased expression of leptin." (PMID 37378223, 2023). "Therefore, leptin is an anti-obesity hormone involved in the control of obesity and weight gain." (PMID 36902744, 2023). "Furthermore, increased muscle lipid oxidation pathways and regulation of muscle differentiation in people with obesity at 52 weeks after metabolic surgery could relate to improved leptin and GH secretion." (PMID 36959287, 2023). "With obesity, elevated levels may also suppress the ability of leptin to inhibit food intake via induction of cellular signaling negative feedback mechanisms such as SOC3 and the tyrosine phosphatase, PTP1B, both of which are increased, specifically in the ArcN." (PMID 36769012, 2023). "In fact, despite the essential role of leptin during lactation, the precise requirements of leptin and whether its beneficial effects during this critical window might depend on particular maternal conditions, such as obesity or exposure to unbalanced/obesogenic diets, are still open questions." (PMID 36771278, 2023). "Besides, low-grade inflammation in obesity leads to leptin resistance." (PMID 37363537, 2023). "These autosomal recessive pathogenic mutations are well studied and differ from the LEP variants that do not lead to monogenic obesity but may be a risk factor of obesity and other metabolic disorders." (PMID 36983642, 2023). "Thus, many other key factors were not included in our analyses, including adipokines like leptin, which are known to be associated with obesity and with cytokine biology." (PMID 37025401, 2023). "However, the blockade of leptin signaling itself may also exert deleterious effects on renal function and injury independently of body weight or obesity." (PMID 37238651, 2023). "Given that reduced leptin transport to the hypothalamus contributes to central leptin resistance, it is reasonable to speculate that proper application of EGF may offer a potential adjuvant therapy for obesity and its associated leptin resistance." (PMID 38027481, 2023). "Moreover, there is no consistency in whether patients with CP possess leptin resistance characterized by elevated leptin levels inappropriate for the degree of obesity." (PMID 37509115, 2023). "Taken together, these data demonstrate that leptin, in contrast to adiponectin, promotes adipose tissue and vascular inflammation and oxidative stress, which may contribute to the development of insulin resistance and vascular disorders during obesity." (PMID 38136564, 2023). "Indeed, in the regression analysis of the present study, the predictors of insulin resistance were visceral fat, adiponectin, and the leptin/adiponectin ratio, which reflect the well-established relationship between central adiposity, inflammatory processes, and obesity comorbidities." (PMID 38063544, 2023). "The reason for leptin resistance is unknown, although there are several known contributing factors that can be attributed to high-fat diet-induced obesity including increased inflammatory signaling, accumulation of lipid metabolites, neuroendocrine axis dysfunction and excessive leptin exposure." (PMID 37571301, 2023). "According to a previous report, endocrine changes related to obesity, such as hyperandrogenism and insulin resistance, and alterations in local insulin-like growth factors, cytokines, adiponectin, and leptin levels, may play a major role in the adverse effects of increased BMI on ART outcomes." (PMID 37684397, 2023). "The crucial question is whether or not the cytokine storm in COVID-19 patients with obesity is linked to leptin dysregulation." (PMID 37240656, 2023). "The IN delivery of the obesity-related hormone leptin has attracted great interest nowadays as it may provide an option to solve leptin resistance, a phenomenon likely due to the impaired transport of leptin across the BBB." (PMID 37371113, 2023).
Obesity (continued). "Previously, hormones such as adiponectin and leptin which play key roles in energy homeostasis and satiety (and are found in human milk but absent from formula) have been hypothesized to contribute to the protective effect of breast feeding against obesity." (PMID 37475022, 2023). "Leptin and adiponectin, hormones produced primarily by adipocytes, are involved not only in glucose and lipid metabolism, controlling energy homeostasis, but also in the modulation of inflammation, appearing to play a role in the relationship between obesity and neuronal/glial function." (PMID 38026693, 2023). "Although we were not able to carry out direct evaluation of humoral and cellular immunity in our children with obesity, we found a high systemic oxidative stress level and a marked depletion of the antioxidant GSH in obese carriers with homozygous loss-of-function mutations in LEP or LEPR genes." (PMID 37659411, 2023). "Thus, obesity caused by leptin deficiency is not the most common in humans, so the potential applications of leptin treatment and its beneficial effects on sleep are limited." (PMID 37571368, 2023). "However, the exact role of these two molecules in the adipose tissue, their contribution to the pathogenesis of obesity, and their interplay with well-established adipokines, such as leptin and adiponectin, is largely unknown." (PMID 37208545, 2023). "Given that LepR-Cre Slc7a5fl/fl mice showed impaired sympathetic tone and leptin insensitivity in LepR-expressing VMH neurons prior to the onset of obesity, we reasoned that LAT1 in LepR-expressing neurons may play an important role in regulating bone homeostasis in addition to energy homeostasis." (PMID 36862514, 2023). "Therefore, the development of leptin resistance in skeletal muscle, characteristic of obesity, may lead to insulin resistance in that tissue by allowing the accumulation of intramuscular lipids and disruption of the insulin signaling pathway." (PMID 36998471, 2023). "To clarify the effects of hepatic FASN deficiency on NAFLD and diabetes in obese mice in the setting of NCD overfeeding without leptin deficiency, we next studied Mc4r-KO mice as an alternative mouse model of hyperphagic obesity associated with hepatic FASN upregulation and hyperleptinemia." (PMID 37681411, 2023). "Leptin resistance may develop when the serum leptin concentration rises during obesity." (PMID 37789370, 2023). "Therefore, it is important to consider the mechanisms by which a high fat diet attenuates leptin signaling as described in prior sections as it may have a significant role in the blunted CCK activity commonly seen in HFD-induced obesity." (PMID 37571301, 2023). "Possible mechanisms linking obesity with gastric cancer encompass obesity-associated insulin resistance, abnormally elevated blood levels of insulin-like growth factor (IGF), and associated levels of adipokines such as adiponectin (APN), leptin, steroid hormones and cytokines." (PMID 37954072, 2023). "Thus, fasting decreases peripheral leptin levels, while feeding or obesity increases leptin levels." (PMID 36674935, 2023). "The impact of breastfeeding on obesity-related asthma The link between obesity, asthma, and a short period of exclusive breastfeeding indicates a shared mechanism, which could be mediated by leptin." (PMID 37789370, 2023). "In obesity, white adipose tissue shows increased infiltration by immune cells such as macrophages, that secrete proinflammatory cytokines such as tumor necrosis factor alpha and interleukins 1β and 6, whose production is also stimulated by the described changes in adiponectin and leptin." (PMID 37364149, 2023). "Moreover, plasma leptin concentration was evaluated as a marker of diet-induced obesity." (PMID 37770988, 2023).
Obesity (continued). "Furthermore, anti-obesity and insulin sensitizing effects have also been endorsed by the modulating potential of C. odorata and coumarin on adipokinin levels (leptin, adiponectin, and chemerin), and inflammatory (TNFα, IL-6) and oxidative stress biomarkers (CAT, SOD, MDA)." (PMID 37033655, 2023). "We postulated that hypothalamic Slug might promote obesity by inducing leptin resistance." (PMID 36512408, 2023). "The study focused on increased leptin levels attributable to obesity as the cause of T cell exhaustion; however, the precise mechanisms underlying the improved efficacy of anti-PD-1 treatment in obesity were not clarified." (PMID 34091744, 2022). "Moreover, a review published in 2018 brought new insights into the role of the LEP/LEPRb axis in obesity-mediated cancers via the JAK/STAT, MAPK, and PI3K/AKT pathways, which are related to cell proliferation, cell migration and invasion, angiogenesis, vascular stimulation, and apoptosis." (PMID 35563103, 2022). "It has been shown that in obesity, there is a decrease in the proliferative capacity of T cells, production of interferon gamma (IFNγ) and TNF-α, and increased expression of PD-1, which may be associated with leptin signaling." (PMID 35164764, 2022). "However, whether and how gut microbiota mediate changes of leptin sensitivity/resistance in health and obesity are still unclear." (PMID 35865314, 2022). "Interplay between hormones and cytokines may also be important as TNFα, which reduces insulin sensitivity and has been shown to be overexpressed in people with obesity, is partially mediated by leptin in addition to IL-2, and IL-6 cytokines that increase T-cell expansion and liver disorders." (PMID 36143948, 2022). "In an attempt to study obesity, various models based on ordinary differential equations considering regulations in energy and metabolism, as well as on the effects of different hormones such as ghrelin, cholecystokinin, and leptin have been hypothesized." (PMID 35480480, 2022). "The results of studies have suggested that leptin could be the link between obesity and cancer." (PMID 35328822, 2022). "The underlying cellular and molecular mechanisms for maternal programming of adult obesity remain unclear; in rodents, hormonal signals during early postnatal development, including leptin, insulin and ghrelin, mediate these effects—at least in part—via the CNS." (PMID 34475504, 2022). "The obesity-induced adolescent hypertension may be mediated partly by the activation of the sympathetic nervous system, which included insulin resistance and secretion of leptin." (PMID 36210942, 2022). "Additionally, individuals with DS have physiological profiles that may contribute to obesity and could impact weight loss (e.g., hypotonia, decreased REE, increased leptin, cardiac chronotropic incompetence)." (PMID 36819200, 2022). "In general, our study showed that chitosan at 3/g/d for 12 weeks improved all obesity-related cardiometabolic markers (anthropometric indicators of obesity and lipid and glycemic markers) assessed as well as appetite-related hormones (adiponectin, leptin, and NPY)." (PMID 36064382, 2022). "Cytokines such as TNFa and leptin that are already increased during pregnancy and, in the setting of obesity, may be further exacerbated by the bacterial overgrowth, dysbiosis, and increased vascular permeability seen during low level gastrointestinal inflammation." (PMID 36584051, 2022). "Based on this finding, we hypothesized that obesity in mothers would have an impact on the knee cartilage of their offspring and that alterations in leptin-mediated signaling pathways might also be one of the mechanisms involved in the mediation of cartilage health." (PMID 35327669, 2022). "The hormone leptin is produced by the LEP gene, which is involved in regulating appetite; therefore, changes in its expression may predispose to obesity and associated non-communicable diseases in adulthood." (PMID 35629277, 2022).